FBXO48 (F-box protein 48)
Tractability: No criterion of Open Targets' tractability assessment is met for any kind of drug.
Gene: Protein-coding gene on chromosome 2 (68,459,422 to 68,467,317, reverse strand). Ensembl gene ENSG00000204923.
Subcellular location (Human Protein Atlas): Nuclear bodies
Gene Ontology:
Molecular function: protein binding; ubiquitin-like ligase-substrate adaptor activity
Biological process: SCF-dependent proteasomal ubiquitin-dependent protein catabolic process
Genetic constraint (gnomAD): Loss-of-function variants: 12 observed, 15.16 expected, observed/expected ratio (o/e) 0.79, 90% interval 0.51 to 1.28. The upper end of that interval is the gene's LOEUF score, 1.28, which puts it in group 5 of 6, group 1 being the genes least tolerant of losing a copy. Missense variants: 177 observed, 187.17 expected, observed/expected ratio (o/e) 0.95, 90% interval 0.84 to 1.07. Synonymous variants: 53 observed, 65.03 expected, observed/expected ratio (o/e) 0.81, 90% interval 0.65 to 1.02.
Homologues: Orthologues: chimpanzee FBXO48 (99% identical), macaque FBXO48 (94% identical), dog FBXO48 (86% identical), guinea pig FBXO48 (86% identical), pig FBXO48 (85% identical), rabbit FBXO48 (85% identical), mouse Fbxo48 (75% identical), rat Fbxo48 (71% identical), zebrafish fbxo48 (50% identical), tropical clawed frog fbxo48 (34% identical).